S100A4 (S100 calcium binding protein A4)
Diseases named in the same sentence as S100A4 in open-access papers (continued):
Sharing a sentence is not in itself a finding about the gene and the disease.
lung carcinoma (continued). "Here, we found that both extracellular treatment and intracellular overexpression of S100A4 suppressed autophagy and increased cell viability in lung cancer cells." (PMID 29449540, 2018). "Our study extends current understanding by showing that at physiologically achievable levels, niclosamide can effectively target the S100A4/NF-κB/MMP9 signaling axis in lung cancer by decreasing S100A4 expression." (PMID 27127879, 2016). "Recent studies demonstrate that S100A4 promotes lung cancer cell mortility and cell growth, although the detailed mechanisms have not been fully defined." (PMID 27127879, 2016). "Collectively, these results implicate S100A4 in driving lung cancer invasive potential, at least in part, through activation of the NF-κB/MMP9 axis." (PMID 27127879, 2016). "Collectively, this study highlights the importance of the S100A4/NF-κB/MMP9 axis in lung cancer invasion and provides a rationale for targeting S100A4 to combat lung cancer." (PMID 27127879, 2016). "Our data demonstrate that S100A4 drives the invasive capacity of lung cancer cells, affects the NF-κB pathway, and acts as an essential component of TNF-α-induced and NF-κB-dependent MMP9 expression." (PMID 27127879, 2016). "Despite extensive investigation of S100A4 in carcinoma progression, the impact of S100A4 signaling in lung cancer is poorly defined." (PMID 27127879, 2016). "Taken together, these data show that S100A4 drives lung cancer invasion by activating NF-κB activity." (PMID 27127879, 2016). "Using established lung cancer cell lines, we demonstrate that S100A4 knockdown reduces cell proliferation, invasion and three-dimensional invasive growth, while overexpression of S100A4 increases invasive potential." (PMID 27127879, 2016). "Niclosamide blocked S100A4 expression in lung carcinomas both at the mRNA and protein levels in a dose-dependent manner." (PMID 27127879, 2016). "Our study highlights the important role of the S100A4/NF-κB/MMP9 signaling axis in promoting lung cancer invasive capacity, and demonstrates that S100A4 overexpression associates with reduced overall survival among patients with lung adenocarcinoma." (PMID 27127879, 2016). "Our data show that S100A4 drives an invasive phenotype in lung cancer cells, thus positioning S100A4 as a potential target for the treatment of advanced NSCLC." (PMID 27127879, 2016). "We used a panel of established lung cancer cell lines with different genetic backgrounds to examine S100A4 expression in lung cancer cells by immunoblot and Q-PCR." (PMID 27127879, 2016). "S100A4 knockout mice, that were otherwise phenotypically normal, were prone to spontaneous tumor development, and the most frequent tumor observed was carcinoma of the lung." (PMID 22853000, 2012). "ANXA10 has been described to be down-regulated in response to up-regulation of S100A4 in a lung cancer cell line." (PMID 21979422, 2011). "First, ANXA10 has been reported to be down-regulated in response to up-regulation of S100A4 in a lung cancer cell line." (PMID 21979422, 2011). "Down-regulation of ANXA10 has been reported in response to up-regulating of S100A4 in a lung cancer cell line." (PMID 21979422, 2011). "It has also been described that S100A4 knockdown enhances the sensitivity of osteocarcinoma cells to undergo apoptosis and reverses the metastatic potential of osteosarcoma and lung carcinoma cells." (PMID 20515499, 2010). "Therefore, we examined the relationship between S100A4 and AE of IP after lung resection for lung cancer." (PMID 34078355, 2021). "Therefore, S100A4 can be not only a predictive factor of AE of IP but also a therapeutic target in patients with IP and lung cancer in the future." (PMID 34078355, 2021). "We examined the usefulness of S100A4 in predicting AE of IP after lung resection for lung cancer." (PMID 34078355, 2021).
lung carcinoma (continued). "Our results demonstrate that S100A4 promoted tumor progression by affecting autophagy, which might be used as a therapeutic target in the development of future lung cancer therapies." (PMID 29449540, 2018). "Downregulation of S100A4 enhances the sensitivity of human lung cancer cells to radiotherapy." (PMID 29449540, 2018). "The S100A4-related microenvironment may provide a promising clinical strategy for lung cancer prevention and treatment." (PMID 29449540, 2018). "Furthermore, in vitro, S100A4 activated β-catenin signaling in lung cancer cells and increased tumor cell viability via inhibiting autophagy in a RAGE-dependent manner." (PMID 29449540, 2018). "Moreover, silencing S100A4 in lung cancer cells significantly increased autophagy and inhibited tumor cell proliferation." (PMID 29449540, 2018). "Although an oral administration of the medicinal mushroom Ganoderma lucidum (GLE) only slightly inhibited cancer growth, it could suppress breast-to-lung cancer metastases by the downregulation of S100A4 expression." (PMID 29069865, 2017). "Importantly, MMP9 inhibition decreased the TNF-α- and EGF-stimulated invasiveness of A549 cells, highlighting the importance of the S100A4/MMP9 axis in S100A4-driven invasion in lung cancer cells." (PMID 27127879, 2016). "Importantly, our study demonstrates that niclosamide dramatically inhibits the NF-κB/MMP9 signaling axis by suppressing S100A4 to block the invasive capacity of lung cancer cells." (PMID 27127879, 2016). "Inhibition of the NF-κB pathway dramatically blocked the invasive capacity of lung cancer cells, suggesting that inhibition of S100A4 signaling could effectively mitigate NF-κB-mediated effects." (PMID 27127879, 2016). "Since niclosamide treatment suppressed S100A4 expression and decreased the invasive potential of lung cancer cells, we hypothesized that treatment with niclosamide would block NF-κB activity." (PMID 27127879, 2016). "Collectively, these data demonstrate that S100A4 drives an invasive phenotype in lung cancer cells." (PMID 27127879, 2016). "Taken together, these data suggest that S100A4 could serve as a marker of poor prognosis as well as a valuble therapeutic target in lung cancer." (PMID 27127879, 2016). "VIM is not believed to be associated with survival in lung cancer, although S100A4 has been correlated with prognosis of lung squamous cell carcinoma in clinical research studies." (PMID 22761930, 2012). "We determine whether the modulation of hsa-miR-125b-5p and MMP-2 by S100A4-RAGE signaling in human lung cancer cells (A549) involves the activation of mitogen-activated protein kinases (MAPKs), including p38-MAPK, Jun kinase (JNK/SAPK), and extracellular signal-regulated kinase (ERK) pathways." (PMID 41155277, 2025). "In addition, complex I activity could also be increased when its auxiliary subunit is upregulated, given that S100 calcium-binding protein A4 was reported to enhance complex I activity in lung cancer cells by upregulation of NDUFS2." (PMID 37186123, 2023). "In this study, we investigated the contribution of S100A4 in lung cancer cell invasion, determined the clinical significance of S100A4 expression in patient-derived lung cancer tissues, and provided a rational for targeting S100A4 signaling through repurposing an FDA-approved drug." (PMID 27127879, 2016). "Therefore, we investigated whether niclosamide also suppresses S100A4 expression in lung cancer cells and whether it inhibits S100A4-mediated functions." (PMID 27127879, 2016). "In this work, we investigate the interaction between hsa-miR-125b-5p and MMP-2 in lung cancer cells A549 and SHP-77, with a particular emphasis on the effect of RAGE activation via S100A4." (PMID 41155277, 2025). "Taken together, SFPQ is present on the cell surface and affects cell function via interaction with S100A4, PPIA, etc. in lung cancer and other solid cancer cells." (PMID 40770831, 2025).
lung carcinoma (continued). "One of the significant contributors to lung cancer progression is the receptor for advanced glycation end products (RAGE), which is activated by its ligand S100A4." (PMID 41155277, 2025). "The S100A4/NDUFS2 axis reshapes mitochondrial metabolism and promotes the invasion and metastasis of lung cancer." (PMID 39179991, 2024). "In support of our study, recent work has shown that both S100A4 and MMP9 are upregulated in patient-derived lung cancer tissues and positively correlate with each other, further implicating the importance of S100A4/MMP9 signaling in lung cancer progression." (PMID 27127879, 2016). "We constructed a lung cancer tissue microarray (TMA) and stained sections for S100A4 using immunohistochemistry in order to examine S100A4 expression in patient-derived tissues (N = 212)." (PMID 27127879, 2016). "Expression of S100A4, PCNA and c-fos were reduced in STAT1- and STAT1-CC-expressing lung cancer cells, while PCNA and c-fos were decreased to a greater extent in STAT1-CC cells." (PMID 26351076, 2015). "Here, we investigated whether NF-κB activation is involved in S100A4-RAGE-induced modulation of hsa-miR-125b-5p and MMP-2 in human A549 lung cancer (LC) cells." (PMID 41155277, 2025). "To investigate whether S100A4-RAGE signaling influences hsa-miR-125b-5p and MMP-2 expression through JNK-MAPKs or ERK-MAPKs in A549 lung cancer cells, we employed specific MAPK inhibitors." (PMID 41155277, 2025). "In both mouse and human lung cancers, these fibroblasts are ZIP1+S100A4+CX43high CAF." (PMID 36207295, 2022). "Additionally, the upregulation of S100A4, which is considered a mediator of metastasis, has been reported to downregulate ANXA10 in a lung cancer cell line." (PMID 31052599, 2019). "Additionally, up-regulation of S100A4, which is considered a mediator of metastasis, has been reported to down-regulate ANXA10 in a lung cancer cell line." (PMID 21979422, 2011). "In vitro studies revealed that extracellular S100A4 inhibited autophagy and induced Wnt signalling in a RAGE-dependent manner and intracellular S100A4 additionally activated β-catenin, resulting in increased proliferation and enhanced viability of lung cancer cells." (PMID 32722137, 2020). "Regarding the role of S100A4 in colorectal cancer, it comes as no surprise that this protein seems to be related to metastasis, as similar observations were made in other cancer types, such as breast and lung cancer." (PMID 32722137, 2020). "However, the impacts of S100A4 signaling in lung cancer progression and its potential use as a target for therapy in lung cancer have not been properly explored." (PMID 27127879, 2016). "Since fibronectin, β-catenin, S100A4, proliferating cell nuclear antigen (PCNA) and c-fos have been reported to be involved in the control of cell growth or metastasis in cancers, we also evaluated the effect of STAT1-CC on the expression of these proteins in lung cancer cells." (PMID 26351076, 2015). "Young-age patients with NSCLC had a greater extent of malignancy and mortality rate than elderly patients, and most of the young-aged lung cancer patients had ADC, all of which may contribute to the negative relationship between the S100A4 expression and age." (PMID 32696952, 2020).
prostate carcinoma (32 papers, 2009 to 2025). A carcinoma that arises from epithelial cells of the prostate gland. "This prompted us to disclose another role of embigin in promoting prostate cancer cells in association with extracellular S100A4." (PMID 30041429, 2018). "In a syngeneic mouse model of prostate cancer, a S100A4 blocking antibody reduced the overall number of intratumor CD3+ T cells while increasing the number of intratumor CD209+ dendritic cells." (PMID 40078995, 2025). "In experiments on PC3 prostate cancer cells, intracellular S100A4 expression was found to be positively correlated with cell proliferation, revealing that S100A4 promotes cancer cell proliferation." (PMID 38872805, 2024). "This study further demonstrated that S100A4 plays a crucial role in prostate cancer osteolytic metastasis, although IL‐8‐activated EMT is necessary to promote cancer expansion." (PMID 39415352, 2024). "S100A4 accelerates tumorigenesis and the invasion of human prostate cancer through the transcriptional regulation of matrix metalloproteinase-9." (PMID 36499426, 2022). "In this study, we found that S100A4 is up-regulated in bone-metastatic prostate cancer cells, the mtPC3 cells." (PMID 33549040, 2021). "While further examination is required to identify the specific mechanisms of EMT by S100A4 in bone-metastatic prostate cancer cells, our results demonstrate that S100A4 contributes to the EMT process in prostate cancer." (PMID 33549040, 2021). "In this analysis, S100A4 was found to be expressed in various cancer types including prostate cancer." (PMID 33549040, 2021). "Taken together, these data indicate that S100A4 promotes proliferation of bone-metastatic prostate cancer cells by an intracellular mechanism." (PMID 33549040, 2021). "Altogether, we suggest that elevated expression of S100A4 in bone-metastatic prostate cancers contributes to cancer proliferation, migration, and EMT by intra- and/or extracellular mechanisms." (PMID 33549040, 2021). "S100A4 has been reported to mediate proliferation, migration, invasion, and apoptosis in many types of tumor cells, including prostate cancer cells." (PMID 33549040, 2021). "A previous study reported a correlation between EMT in prostate cancer cells and increased expression of S100A4." (PMID 33549040, 2021). "By performing a screen for proteins in pre-operative and post-operative serum from men with high-risk prostate cancer, we identified CASP8, MSLN, FGFBP1, ICOSLG, TIE2, and S100A4 proteins as candidate biomarkers for high-risk prostate cancer." (PMID 33828176, 2021). "Altogether, these results indicate that bone-metastatic prostate cancer cells express high levels of S100A4 mRNA and protein, and secrete a greatly elevated level of S100A4 protein into the extracellular milieu." (PMID 33549040, 2021). "S100A4 has been observed to be overexpressed in advanced-stage thyroid carcinoma and in patients with breast, gastric, pancreatic, lung, and prostate cancers." (PMID 33761962, 2021). "In this study, we divided the functional roles of intra- and extracellular S100A4 in bone-metastatic prostate cancer cells using S100A4 knock-down, recombinant S100A4, and S100A4-neutralizing antibody." (PMID 33549040, 2021). "More detailed mechanisms by which S100A4 mediates EMT in prostate cancers warrant further investigation." (PMID 33549040, 2021). "Taken together, our data show that S100A4 secreted from bone-metastatic prostate cancer interacts with RAGE on osteoclast precursor cells to accelerate osteoclast development." (PMID 33549040, 2021). "Our study demonstrates that S100A4, highly expressed in bone-metastatic prostate cancer cells, has dual intra- and extracellular functions." (PMID 33549040, 2021). "Binding of extracellular S100A4 to embigin mediates prostate cancer progression by inhibition of AMPK activity, activation of NF-κB, MMP9 and mTORC1 signaling, and inhibition of autophagy, which increase prostate cancer cell motility." (PMID 30041429, 2018).
prostate carcinoma (continued). "Embigin also promotes prostate cancer growth, spheroid-and colony-forming ability, and survival upon chemotherapy independently of S100A4." (PMID 30041429, 2018). "As embigin’s roles in cancer remain elusive, we studied its biological functions and interaction with extracellular S100A4 in prostate cancer progression." (PMID 30041429, 2018). "The secretory S100A4 protein in the stroma has pro-growth effects on prostate cancer cells through NF-κB activation upon RAGE binding." (PMID 30041429, 2018). "We also found that embigin promotes prostate cancer growth, spheroid- and colony-forming ability, and survival upon chemotherapy independently of S100A4." (PMID 30041429, 2018). "S100A4 binding contributes mainly to the migration process, suggesting that overexpressed embigin in cancer cells and S100A4 in the surrounding stroma are coordinately functional for prostate cancer progression." (PMID 30041429, 2018). "Further, it is reported that S100A4 protein promotes prostate cancer cell invasion, and malignant phenotypes partially through the transcriptional activation of MMP-9." (PMID 29069865, 2017). "Annexin A10 upregulation in prostate cancer downregulates S100A4 expression and the knockdown of S100A4 expression is found to inhibit prostate cancer cell proliferation, migration, and invasion." (PMID 29069865, 2017). "S100A4 has been shown to be overexpressed during prostate cancer progression in humans and in transgenic adenocarcinoma of the mouse prostate." (PMID 29069865, 2017). "A previous study has shown that ZnR/GPR39 mediates the Zn2+-dependent activation of mitogen-activated protein kinase (MAPK) and PI3K, to induce S100A4 expression and prostate cancer cell invasiveness." (PMID 29069865, 2017). "Study shows that the levels of the mRNA and protein of S100A4 are significantly higher in high-grade prostate cancer specimens compared with benign prostatic hyperplasia, prostatitis, and low-grade prostate cancer." (PMID 29069865, 2017). "In prostate cancer, recent mouse experiments revealed enhanced tumorigenesis of extracellular S100A4-RAGE interaction, by activating the NFκB signaling pathway." (PMID 24952599, 2014). "Similarly, in a syngeneic mouse prostate cancer model, 6B12 treatment reduced the rate of tumor growth, indicating antibody drugs that target S100A4 hold great promise." (PMID 40078995, 2025). "Quantitative analyses of PSA, IL‐8, and S100A4 in prostate cancer patients’ serum specimens." (PMID 39415352, 2024). "We further analyzed the mRNA levels of CASP8 and S100A4 in four different prostate cancer datasets." (PMID 33828176, 2021). "After bone-metastasis, secreted S100A4 from metastatic-prostate cancer cells may promote osteoclastogenesis via RAGE, leading to bone destruction." (PMID 33549040, 2021). "Therefore, targeting S100A4/embigin-mediated signaling is a potential prostate cancer therapeutic approach for prostate cancer patients." (PMID 30041429, 2018). "The binding of extracellular S100A4 to embigin mediates prostate cancer progression by orchestrating multiple mechanisms including inhibition of AMPK activity, activation of NF-κB, MMP9, and mTORC1 signaling, and inhibition of autophagy, which lead to an increase in cellular motility." (PMID 30041429, 2018). "This suggests embigin might affect prostate cancer growth by its interaction with either MCT2 or other MCTs that reprogram cancer metabolic activity independently to S100A4." (PMID 30041429, 2018). "We proposed that embigin and p21WAF1 could be used as prognostic biomarkers and a strategy to inhibit S100A4-embigin binding could be a therapeutic approach for prostate cancer patients." (PMID 30041429, 2018). "Moreover, S100A4 accelerates tumorigenesis and invasion of human prostate cancer by transcriptional regulation of MMP9." (PMID 30041429, 2018). "S100A4 is an important oncoprotein that promotes prostate cancer progression and dissemination." (PMID 29069865, 2017).